KRT19 (keratin 19)
Diseases named in the same sentence as KRT19 in open-access papers (continued):
Sharing a sentence is not in itself a finding about the gene and the disease.
tumor (continued). "Immunohistochemically, the resected tumor stained positively for the epithelial markers, epithelial membrane antigen (EMA) and cytokeratin 19 (CK 19), and the mesenchymal markers, smooth muscle actin (SMA) and vimentin." (PMID 23426899, 2013). "Thorough validation in clinical samples revealed that KRT19, CEACAM5, SFTPA, SFTPC and DSG3 were promising markers for tumor cells in LNs and PB from NSCLC patients." (PMID 23671585, 2013). "We selected three genes, the known tumor suppressors KLF11, DLEC1, and KRT19 and verified promoter hypermethylation, mRNA repression and protein expression using bisulfite sequencing, real-time PCR and western blot." (PMID 22428009, 2012). "We verified the effects of promoter DNA methylation on transcriptional inhibition of three tumor suppressor genes namely, KLF11, DLEC1, and KRT19." (PMID 22428009, 2012). "Our aim was to specifically quantify the fecal cytokeratin 19 (CK19) transcript from CRC patients and investigate its correlation with clinical stage, tumor malignancy, and age." (PMID 19849844, 2009). "Serum tumor markers (TMs) have long been considered metabolites of tumor tissue, including carcinoembryonic antigen (CEA), carbohydrate antigens (CA125, CA15-3, and CA19-9), cytokeratin-19-fragment (CYFRA21-1) and neuron-specific enolase (NSE)." (PMID 40171507, 2025). "The selection of A498 cells was informed by prior evidence demonstrating their responsiveness to 5-Aza-CdR-mediated demethylation and reactivation of tumor suppressor genes (e.g., WNT7A, KRT19, BTG3), confirming sufficient endogenous DNMT activity for pharmacological inhibition." (PMID 40866976, 2025). "Silencing of KRT19 potently induces senescence program in NSCLC cells and boosts anti-PD-1 immunotherapy efficiency by potentiating stronger antineoplastic responses of tumor-infiltrating cytotoxic CD8+ T cells." (PMID 41345704, 2025). "Some patients may also have elevated tumor markers like SCC, carcinoembryonic antigen (CEA), CA-125, CA19-9, and cytokeratin 19 fragment." (PMID 41040533, 2025). "CAFs and tumor cells were identified using DCN and KRT19, respectively." (PMID 40215177, 2025). "Lastly, we performed co-expression analysis of DUSP6 and KRT19 and found a 1.8-fold increase in DUSP6 positive cells in PDAC KRT19 positive cells compared to healthy pancreata, confirming DUSP6 upregulation in tumor epithelial cells." (PMID 41028058, 2025). "Laboratory tests revealed leukocytosis (white blood cell count, 10 960/μL), elevated lactate dehydrogenase (401 U/L), and markedly increased tumor markers, including carcinoembryonic antigen (CEA) (525.1 ng/mL) and cytokeratin 19 fragment (CYFRA 21‐1) (46.5 ng/mL)." (PMID 41350121, 2025). "Other genes: BTG1, CD24, KRT19, RAC2 and RGS1 were significantly upregulated in tumour samples." (PMID 39098994, 2024). "However, we also noted an increase in the expression of certain tumor related genes, including SAA1, KRT19 and NUPR1." (PMID 38951896, 2024). "Most nonimmune cells in iCCA tumors were epithelial-derived tumor cells with high expression of KRT19 and EPCAM." (PMID 38245530, 2024). "Moreover, the most differentially expressed mRNA in KCs from tumour-bearing mice included epithelial mRNA such as cytokeratins 8 (Krt8) and 19 (Krt19), which is compatible with the phagocytosis of KPC tumour cells, although a contamination cannot be excluded." (PMID 38326607, 2024). "Immunohistochemically, the tumor cells displayed positivity for cytokeratin 19 and p63 while testing negative for myoepithelial markers." (PMID 38298294, 2024). "The original tumors were positive for AFP and HepPar1 similarly to transplanted HepYF-M13 tumors but showed reduced Sox9 and no significant Krt19 expression in tumor cells." (PMID 39051113, 2024).
tumor (continued). "Besides the varied expression of markers indicative of malignant tumour behaviour in malignant cells, our study also revealed distinct expression patterns of different keratins, namely, KRT5 and KRT19, at the transcriptome level in epithelial cells." (PMID 37349991, 2023). "Tumor markers: gastric protease I, gastric protease II, alpha-fetoprotein (AFP), carbohydrate antigen, cytokeratin 19 fragment, gastrin-releasing peptide precursor, total prostate-specific antigen, free prostate-specific antigen, carcinoembryonic antigen, neuron-specific enolase." (PMID 38115262, 2023). "For example, 88 PEIs were correlated with the cytokeratin-19-fragment CYFRA21-1 (CYFRA 21-1); 83 PEIs were correlated with tumor-supplied group factors; 64 PEIs were correlated with neuron-specific enolase; and 64 PEIs were correlated with complex prostate-specific antigen (C-PSA)." (PMID 36379988, 2022). "A previous study has found that HCC with low expression levels of stemness-related markers, such as keratin 19 or epithelial cell adhesion molecule (EpCAM), could show better outcomes after TACE, such as fewer residual tumors and more complete tumor necrosis." (PMID 35111225, 2022). "However, in recent years, scholars have mostly focused their prognosis for patients on the impact of tumor cells or the tumor microenvironment, such as CD47 expression and CD163+ macrophages, cytokeratin-19 (CK-19), and tumor-infiltrating platelets." (PMID 36159473, 2022). "The tumor cells were positive for Hep Par-1, Arginase 1 (ARG1), CD10, Glypican-3 (GPC3), and KRT19." (PMID 35789568, 2022). "Epithelial makers (KRT18, KRT19, KRT17, KRT7, and CLDN4) were also highly expressed, indicating that M2 may be derived from transdifferentiation of epithelial cells in the tumor." (PMID 35265520, 2022). "As controls, we provide a normal section with intermixed acinar and ductal cells, but lacking a co-staining expression pattern (HT288P1), and a tumor section that is predominantly stained by cytokeratin-19 (HT190P1)." (PMID 35995947, 2022). "It has been reported that molecular detection of tumour markers such as carcinoembryonic antigen (CEA), cytokeratin 19 (CK-19), cytokeratin 20 (CK-20) is better correlated with peritoneal recurrence and associated with adverse outcomes in patients with GC10,17–19." (PMID 35864130, 2022). "Moreover, the relationship between KRT19 expression and immune infiltration of BRCA tumor cells was analyzed." (PMID 36292723, 2022). "As validation, we performed immunofluorescence staining on tumor and normal formalin-fixed paraffin-embedded (FFPE) sections with amylase (acinar), cytokeratin-19 (ductal), Hoechst (nuclei) and Ki67 (proliferation) to evaluate co-staining patterns within individual cells." (PMID 35995947, 2022). "Tumor cells can be divided into 4 different subtypes, including basaloid cells (KRT5, KRT14), myoepithelial cells (ACTA2, MYL), cycling cells (MKI67, TOP2A) and duct-like cells (KRT7, KRT19)." (PMID 35860547, 2022). "Tumors comprised of Krt19-edited PDA cells that combined icOVA expression with an absence of the CXCL12–KRT19 coating exhibited a further reduction of tumor growth rate, and by day 30, four of five tumors were no longer detectable." (PMID 35046049, 2022). "In addition, epithelial cell differentiation regulation-related genes, such as AKR1B1, SPRR1B, and keratin genes KRT6A, KRT19, and KRT17 were also highly expressed in mixed-lineage tumor cells." (PMID 35962452, 2022). "Along with the trajectory, epithelial cell marker EPCAM and ductal marker KRT19 exhibited sustained high expression levels during PDAC progression, while genes previously reported to be involved in tumor progression, such as MUC1 and CEACAM6, gradually upregulated along with the transition." (PMID 34732701, 2021). "LC-IPF patients had larger tumor diameters and higher level of cytokeratin 19 fragment (Cyfra) than LC-non-IPF patients." (PMID 34702952, 2021).
tumor (continued). "Finally, compared to macroH2A1 KD Huh-7 cells, FAK KD cells exhibited a significant reduction (p < 0.01) in the mRNA levels of tumor-promoting genes CCL2, EGF, BAX, KRT19, EGFR, NOTCH1, ABL1, and SMAD3." (PMID 33182805, 2020). "The tumor marker cytokeratin 19 fragment (CYFRA 21-1) is a fragment that exists in many normal as well as malignant epithelial cells." (PMID 31940100, 2020). "Furthermore, a list of genes, including AZGP1, KRT19, and PIGR, was identified as differentially expressed between TNBC and other tumor types, suggesting their potential use as discriminatory markers." (PMID 31134153, 2019). "Three of the luminal markers KRT7, KRT19 and CD24 showed staining in the tumor transplants." (PMID 30550540, 2018). "Then Receiver Operating Characteristic curve (ROC) analysis was performed to compare the diagnosis accuracy among miRNAs or traditional tumor markers such as carcino embryonie antigen (CEA), cancer antigen 199 (CA199), cytokeratin 19 fragments (CYFRA21-1), and squamous cell carcinoma antigen (SCC)." (PMID 28178679, 2017). "Tumor differentiation and microvascular invasion were shown to have significant associations with the expression of NKCC1 (p<0.05), keratin 19 and Ki-67 but not glypican-3." (PMID 29029515, 2017). "For example, the sensitivity of detecting circulating tumor antigens, such as CA125, CA199, neuron specific enolase (NSE), carcinoembryonic antigen (CEA), and cytokeratin 19 fragment (CYFRA 21–1) is only 5.0%, 4.9%, 19.7%, 17.2%, and 26.5%, respectively, in patients with stage I NSCLC." (PMID 29021294, 2017). "The tumor nodules analyzed stained positively for glutamine synthase and were negative for cytokeratin 19, indicating that the tumors originated from the hepatocyte and not the cholangiocyte lineage." (PMID 28120397, 2017). "An evaluation of molecular signatures based on tumor expression of 20 metastasis-associated microRNAs, a comparison of microRNA expression between tumor and adjacent benign tissue, or the tumor expression of five genes (HN1, RAN, RAMP3, KRT19 and TAF9) can also predict prognosis." (PMID 28943622, 2015). "Notably, keratin-19 (KRT19), a well-established marker of circulating tumor cells and CSCs, is increased by >20-fold in MCF7-FOXM1 cells." (PMID 26087310, 2015). "KRT19 is a characteristic marker of epithelial cells, whereas FAM83A is a novel biomarker for detection of the peripheral blood, which was identified as a tumor-specific gene in our previous study." (PMID 24932314, 2014). "RT-qPCR analysis on elderly HCCs demonstrated that the high expression levels of 7 putative hepatic stem/progenitor cell biomarkers (including keratin 19 (K19), ABCG2, CD44, Nestin, CD133, EPCAM and OV6), is related to tumor angiogenesis and a poor prognosis for the HCC." (PMID 24160375, 2013). "Indeed, ER+ tumours were scattered in subgroups 1 to 4 that are characterised by the over-expression of a cluster of genes, which includes CCND1, KRT19, IGF1R, LIV1, ESR1, GATA3, TFF1/pS2, ERBB4, PR and IGFBP4." (PMID 17338809, 2007). "Notably, compared to KPPS model, the surrounding normal pancreatic tissue in KPPC tumours exhibited upregulation of Krt19 and downregulation of acinar cell markers, suggesting that the pancreatic tissue adjacent to KPPC tumours may be undergoing ADM." (PMID 40717219, 2025). "Therefore, in this study we aim to comprehensively assess the diagnostic value of individual and combined detection of serum IL-6 with traditional tumor markers, such as carcinoembryonic antigen (CEA) and cytokeratin 19 fragment (CYFRA21-1), in AIS patients in a large cohort of 300 cases." (PMID 38529301, 2024). "We demonstrated that the mouse PDA tumor was a suitable model for this analysis by showing that the KRT19+ cancer cells in subcutaneous (s/c) PDA tumors were coated with CXCL12, as assessed by imaging nonpermeabilized sections that had been stained with antibodies to KRT19 and CXCL12." (PMID 35046049, 2022).
tumor (continued). "As new immunotherapies and targeted therapies are revealed, our findings suggest value in further investigations into a panel of personalized tumor markers, which may include proteins with therapeutic relevance such as FOLR1, KRT19, KLK6, PARP-1, TROP2, and IFNL1." (PMID 34868557, 2021). "However, segregation of the patients into KRT19-high and low expression groups did not reveal significant relationship with clinicopathological parameters of sex, age, tumor size, location, grade." (PMID 33442422, 2021). "Although HCC cells are not derived from cytokeratin 19 (Krt19) or osteopontin (Spp1) expressing biliary epithelial cells, they express higher levels of Prom1 compared to non-tumor tissues, suggesting the contribution of hepatocyte-derived PROM1+ cells in HCC formation." (PMID 33173221, 2020). "Indeed, IHC analysis highlighted a specific KRT19 staining only in tumour cells but not in the stroma." (PMID 32376891, 2020). "Surprisingly, deposits from KRT19 negative primary neoplasms can be positive for KRT19 in LNs too." (PMID 31331335, 2019). "Interestingly, the only two tumors with higher Krt19 in tumor compared to non-tumoral also showed high expression of Epcam, down-regulation of Cd133, and a slight up-regulation of Afp." (PMID 30177788, 2018). "Cytokeratin 19 mRNA copy number, which distinguishes negative cases (<250 copies), micrometastases (+, ≥250≤5000 copies) and macrometastases (++, >5000 copies), was compared to axillary lymph node dissection status and to the biological tumor profile." (PMID 23533593, 2013). "Notably, we found that the ductal cell markers and epithelial cell-specific markers reported previously, such as EPCAM, KRT18, SOX9, KRT19, MUC1, and FXYD3, were commonly expressed in the majority of clusters except for cluster 17, confirming tumor cell identity." (PMID 37324492, 2023). "However, due to the overly high cell density of the tumour nest and the limited IMC resolution, some adjacent tumour cells and infiltrated immune cells were recognised as epithelial–immune dual feature cells, such as Clusters 4 (KRT5+, KRT19+, CD20+ and CD79A+) and 14 (KRT5+, KRT19+ and LYZ+)." (PMID 37349991, 2023). "Surprisingly, despite the absence of NOX4 in stromal cells, tumours from WT and NOX4-/- mice were identical in size and in the expression levels of Krt19, α-Sma (Acta2) and collagen 1 (Col1a1)." (PMID 40820091, 2025). "Immunohistochemical staining showed that the tumor tissue was positive for CgA, Syn, S - 100, CD10, and CD34, but negative for AFP, cytokeratin 19 (CK19), CK7, GS, GPC3, HSP70, with a Ki-67 labeling index of 2%." (PMID 40978045, 2025). "The levels of tumor markers, including neuron-specific enolase (NSE), squamous cell carcinoma antigen (SCC), and cytokeratin-19 (CYFRA21-1), were higher in the non-MPR group, and the difference was statistically meaningful (P < 0.05)." (PMID 38680859, 2024). "The tumor cells were positive for AE1/AE3, KRT19, Pan-CK, EMA, P40, and P63, and negative for S-100, which were consistent with findings in 2012 and 2015 samples." (PMID 39138533, 2024). "Based on the Western blot results, we performed IHC analysis to study the expression of three proteins, KRT7, KRT19 and SRI, in GSD (non-tumor control), LN negative GBC and LN positive GBC." (PMID 37142981, 2023). "Tumor cells lacked LSEC markers (e.g., CD14) but had bimodal hepatoblast and cholangiocyte marker expression (e.g., the CK19 gene KRT19)." (PMID 36845728, 2023). "Hepatic progenitor cells and cholangiocytes have the tumor markers cytokeratin 7 (CK7) and cytokeratin 19 (CK19), whereas normal hepatocytes do not." (PMID 37726886, 2023). "Coexpression of KLK6 with KRT19, αSMA or CD68 was independent of tumour stage, while KLK6 was coexpressed with KRT19 and CD68 in the invasive tumour area." (PMID 34439122, 2021).
tumor (continued). "While DRPs were detected as GFP+ KRT19+ cells in NTL region, tumor cells were also labeled with GFP but not for KRT19." (PMID 33173221, 2020). "Tumor cells were positive for AFP and Hep par 1 (HEP) stains but negative for cytokeratin 19 (CK19)." (PMID 32235007, 2020). "We did not observe any changes in levels of amylase or cytokeratin 19, or the mucins MUC1, MUC2 or MUC5AC in rapamycin-treated KC PTEN tumours." (PMID 24717934, 2014). "Following the criterion, we identified KRT19 is highly expressed in NSCLC but not normal tissues, targeting of which not only induces NSCLC cell senescence, but also enhances the function of tumor-infiltrating CTLs and synergistically represses NSCLC progression when combining with anti-PD-1." (PMID 41345704, 2025). "Additionally, to assess the contamination of tumour cells in metastatic samples, we examined the expression of oesophageal epithelium genes (KRT5, KRT19, EPCAM and SOX4) and found almost no cells that expressed these genes." (PMID 36650114, 2023). "Furthermore, staining of the epithelial marker, cytokeratin 19 (CK19), revealed a dichotomous expression pattern in these tumors with areas of positive as well as negative staining within the tumor mass." (PMID 34292968, 2021). "Third, other predictive biomarkers, such as radiomics features, carcinoembryonic antigen (CEA), cytokeratin 19 fragment (CYFRA21-1), epidermal growth factor receptor (EGFR), circulating tumor cells, and circulating cell-free DNA were not analyzed in the current study." (PMID 33292228, 2020). "We sequentially extracted the tumor specimens with Nonidet P-40, sodium deoxycholate (DOC), DNase, and sodium dodecyl sulfate (SDS) and analyzed the lysates by SDS-polyacrylamide gel electrophoresis (SDS-PAGE) and immunoblotting with anti-KRT19 and anti-CXCL12 antibodies." (PMID 35046049, 2022). "Furthermore, the staining of cytokeratin 19 (CK19), a marker of biliary lineage cells, showed no immunoreactivity to CK19 in the tumor tissues from the C57-HBV mice delivered with sgp53/Pten even though significant CK19 staining could be detected in the adjacent non-tumor tissues (third row)." (PMID 28584302, 2017).